IFNG (interferon gamma)
Diseases named in the same sentence as IFNG in open-access papers (continued):
Sharing a sentence is not in itself a finding about the gene and the disease.
tumor (continued). "Interferon-gamma (IFNG), which is an important cytokine for initiating and maintaining a potent anti-tumor response in multiple pathways, has been considered a useful predictor of response to anti-PD1/PDL1 therapy across various tumors." (PMID 35493449, 2022). "Tumor-specific IFNγ-producing T cells persist during cell-induced leukopenia, while Tregs are gradually eliminated, especially within tumors." (PMID 35745800, 2022). "IFNγ has both protumor and antitumor activities, although it induces the Th1-recruiting, proinflammatory chemokines in the tumor microenvironment." (PMID 35223517, 2022). "IFNγ signaling also enhances tumor eradication by blocking the functions of some suppressive immune cells in the tumors, including Tregs." (PMID 35606804, 2022). "According to our data, the T-cell polarization ability of DCs altered by different tumor cell lines promotes the development of IFNγ or IL-10-producing T cells, but different tumors induce diverse responses." (PMID 36194602, 2022). "In consensus, IFNG enhanced human immune function, protected normal cells from infection and tumor transformation." (PMID 35692844, 2022). "Immunotherapies such as ICB, oncolytic viral vaccines, and immunostimulatory therapies using STING agonists suppress tumor angiogenesis, often through IFNγ, GAMs, and CD8+ T cells." (PMID 36140392, 2022). "Th1 signatures, typically denoted by IFNγ and CD40L (as we observed), are known to be associated with a more anti-tumor TME phenotype and ICB responsiveness." (PMID 36309495, 2022). "CD8+ cells are regarded as being a uniform population of cells that largely and quickly secret IFNγ and a protease, GzB, which can kill tumor cells." (PMID 35217706, 2022). "Overall, parental B16-F10 and control cells demanded at least tenfold higher concentration of IFNγ to achieve a comparable response seen in Stub1-null cells, suggesting Stub1 is a key checkpoint for IFNγ sensing in tumour cells." (PMID 35982220, 2022). "These transcriptional changes also led to increased protein expression of ISG, as evidenced by an increased proportion of IFNγ-induced CXCL9-secreting tumor cells after treatment with MRTX." (PMID 35857848, 2022). "Nevertheless, we have validated that the combination treatments significantly promoted CD8+ T cell infiltration in hypoxic tumor areas and increased IFNγ expression in the intratumoral CD8+ T and NK cells." (PMID 35840558, 2022). "IFNγ reduces tumor cell proliferation through activation of the transcription factor STAT1, which regulates the kinase inhibitor p21 and inhibits cell cycle progression." (PMID 35163755, 2022). "In line with this, overexpression of Gpx1, an antioxidant target of PGC1α, reduced reactive oxygen species within tumor-infiltrating T cells and boosted IFNγ production." (PMID 35414042, 2022). "Other biomarkers derive from NGS test: tumor mutation burden (TMB) and the level of expression of interferon-gamma (IFNγ) or INFγ gene expression profile signature." (PMID 36304921, 2022). "Reduced Th1 cytokines, IL-12 and IFNγ, in tumor implanted mice increased effectively in PLAG and aPD-L1 treated mice." (PMID 35787261, 2022). "The signal transducer and activator of transcription 4 (STAT4), a member of the STAT family, increases Th1 cell differentiation and IFNγ production in immune cells and regulates tumor cell migration and proliferation." (PMID 35873566, 2022). "On the one hand, IFNG is a potent inducer of the adaptive immune response, promoting antigen presentation and effector T cell activity, and catalyzing immune-mediated tumor clearance." (PMID 35492352, 2022). "Tumor cell lysis can also induce the production and secretion of inflammatory mediators, including type I interferons (IFNs), interferon-gamma (IFN-γ), interleukin-12 (IL-12), and tumor necrosis factor-α (TNF-α)." (PMID 35295845, 2022).
tumor (continued). "Pro-inflammatory cytokine production including tumor necrosis factor α (TNFα), IFNγ, and IL-2 were significantly elevated in tumor-infiltrating CD8 + T cells from Salmonella + Alb-IL2 treated mice compared to mice treated with Salmonella or Alb-IL2 alone." (PMID 35962391, 2022). "SPF and ex-GF mice (reconstituted with SPF microbiota) developed larger PDAC tumors with decreased NK cell tumor infiltration and IFNγ expression versus GF-Rag1−/−." (PMID 35980869, 2022). "A study by Wang and colleagues found that CD8+ T cells activated by immune checkpoint blockade were able to promote ferroptosis-specific lipid peroxidation in tumor cells by secreting interferon gamma (IFNγ)." (PMID 36033530, 2022). "Autologous in vitro differentiated moDCs were then pulsed with the tumor cell lysate in the presence of lipopolysaccharide (LPS) and IFNγ." (PMID 36011029, 2022). "In tumor-bearing mice receiving three doses of IFNγ, however, only a minor increase in the tumor uptake of the tracer was observed." (PMID 35745666, 2022). "For functional analysis of CRISPR/Cas9-engineered T cells, we assessed T cell activation by IFNγ-Elispot and tumor cell apoptosis (cleaved-PARP) by Western blot." (PMID 36428578, 2022). "The serum level of IL-12 was significantly higher in the tumor-bearing mice than in the tumor-free mice; moreover, the tumor-bearing mice also displayed a trend toward higher serum levels of IFNγ, IL-5, and IL-6." (PMID 35805045, 2022). "Inhibiting EGFR signaling restores the expression of major histocompatibility complex (MHC) molecules, and enhances secretion of interferon-gamma (IFNγ) which increases PD-L1 expression on tumor and immune cells within the tumor microenvironment (TME)." (PMID 35372020, 2022). "elucidated that IFNγ and lymphocytes in the immune system can cooperate to suppress tumor development, consistent with our results with elevated B cells, Type-II-IFN response in the low-risk group." (PMID 36120466, 2022). "IFNγ also increases tumor cell death by increasing the expression of Fas and TRAIL and potentiates increased apoptosis by upregulating the expression of multiple caspases." (PMID 35163755, 2022). "For effective activation of anti-tumor immunity, the present work focused on the well-established IFNγ pathway, whose activation in both tumor and immune cells in the microenvironment constitutes a key part of the natural tumor immune surveillance program." (PMID 35304449, 2022). "Following in vitro stimulation with immunodominant peptides, the CMV-specific CD8+ T cells reverse their competent cytolytic function to release several cytokines, including TNF-α and IFNγ that are involved in several anti-tumor immune responses." (PMID 35515137, 2022). "TIL pretreated with any of the compounds resulted in increased recognition of their autologous tumor cells measured by IFNγ production, especially after exposure to H2O2, as compared with the control group." (PMID 35738800, 2022). "High tumor infiltration by CD8+ lymphocytes was associated with longer OS and PFS of patients with aUC treated with pembrolizumab, and high expression of IFNγ in the TME was significantly correlated with favorable PPS." (PMID 35053427, 2022). "Avenues of investigation include exploring the role of pro-tumoral IFNγ and TGFβ signalling (immune-suppressive), which are predicted to globally impact the recruitment, expansion, and function of immune cells in the tumour microenvironment." (PMID 36612154, 2022). "The interferon-gamma (IFN-γ) signature measures the expression of up to 25 genes involved in tumor-related inflammation." (PMID 35406412, 2022). "In the TME, IFNγ elaborated by tumor-specific CD8+ T cells induces expression of lymphatic PD-L1, which limits local CD8+ T-cell tumor infiltration in various murine melanoma models and MC38 colon adenocarcinoma." (PMID 35216243, 2022).
tumor (continued). "This is in line with previous reports showing that downmodulation of JAK1 and JAK2, both essential tyrosine kinases in the IFNγ-signaling pathway, in tumor cells results in resistance to CD3 bsAbs." (PMID 36271507, 2022). "In fact, pre-clinical and clinical studies have proven that an induction of IFNγ is required for the activation of a potent anti-tumour immune response." (PMID 35158816, 2022). "GO analysis revealed the significant variation of biological processes in cDC-AREG in high tumor infiltration group, including “response to interferon-gamma”, “response to reactive oxygen species” and “reactive oxygen species metabolic process”." (PMID 36532059, 2022). "T-cells infiltrating tumor tissues secrete interferon-gamma (IFN-γ), which triggers regulatory immunosuppressive loops, including PD-L1 expression." (PMID 36291806, 2022). "We showed that virus-derived IFNγ synergised with a TLR2/1 agonist to induce nitric oxide production in macrophages as a strong proinflammatory signal of anti-tumour macrophage programming leading to tumour inhibition." (PMID 35804458, 2022). "Glucose deprivation can prevent tumor-infiltrating CD8+ cells from functioning by altering interferon gamma production." (PMID 35629102, 2022). "Immune cells (e.g., CTLs, NK cells, NKT cells, γδ T cells, and DCs) translocate in tumor sites and secrete various cytotoxic effectors, such as anti-angiogenic interferon-gamma (IFN-γ) and IL-4, perforin and granzyme." (PMID 36298472, 2022). "Mechanistic investigation showed STING mediated myeloid/CXCL9-CD8+ T/IFNγ feedback loop after intratumoral vaccination, which led to increased infiltration of tumor-specific cytotoxic T cells for tumor eradication." (PMID 35623658, 2022). "Monocytes from PBMCs were cultured in a medium with GM-CSF and IL-4, followed by pulsing with hypochlorous acid (HOCl)-oxidized whole tumor lysate and maturation with LPS and IFNγ." (PMID 36011029, 2022). "Destruction of tumor cells by OVs results in the release of tumor-specific antigens (TSA), PAMPs, danger-associated molecular patterns (DAMPs), and cytokines (TNFα, IFNγ, and IL-12)." (PMID 36678780, 2022). "While collaborations between CD8+IFNγ+ and CD4+IFNγ+ T cells are needed to kill tumor cells, several studies have reported that both of these cell types are suppressed in cancer patients during disease progression." (PMID 35053375, 2022). "IFNγ, produced by T cells, recognizes the corresponding receptors on tumor cells or antigen-presenting cells, producing antitumor response." (PMID 36185620, 2022). "Lymphocytes are often able to inhibit tumor proliferation and metastasis, and kill tumor cells through their immune function (secrete interferon gamma (INF-γ) and tumor necrosis factor (TNF-α))." (PMID 35932022, 2022). "Enhancement of anti-tumor immunity by upregulating antigen recognition and tumor infiltration by T cells then stimulates CD8+ T cells to secrete IFNγ, which forms a positive feedback loop." (PMID 35053427, 2022). "Further evidence to support T cell-mediated tumor immunity came in 1998 and revealed an interferon gamma (IFNγ)-dependent mechanism for inducing tumor immune surveillance." (PMID 35626053, 2022). "Interferon-γ (IFNγ) plays a key role in activating cellular immunity and thus stimulating anti-tumor immune responses." (PMID 34976218, 2022). "SHP1 loss increased macrophage phagocytosis of tumor cells, the ratio of effector to regulatory T cells in the E0771 tumor model, and IFNg in the MC38 tumor model." (PMID 36686648, 2022). "We demonstrated that high levels of CD8+ TILs were significantly associated with a favorable objective response and longer OS, while high IFNγ expression in the tumor was significantly correlated with longer PPS." (PMID 35053427, 2022). "Metformin administration induces interferon-gamma (IFN-γ) production in CD8+ tumor infiltrating lymphocytes in multiple solid tumor models." (PMID 35631452, 2022).
tumor (continued). "Interferon-gamma is usually produced by activated T cells and NK cells and is responsible for inhibiting the growth of tumor cells." (PMID 35769464, 2022). "For example, CD8(+)T cells release interferon-gamma (IFNγ) to inhibit the glutamate-cystine antiporter system xc-, enhance lipid peroxidation, and promote ferroptosis in tumor cells." (PMID 35611986, 2022). "GSEA revealed 15 pathways enriched significantly in epithelial cells of residual tumor, including inflammatory response, interferon alpha and interferon gamma response, as well as PI3K/Akt/mTOR signaling and mTORC1 signaling pathways." (PMID 35784460, 2022). "In parallel, human NK cells, isolated and sequenced from non-small cell lung cancer patients, had higher HIF1a expression and lower IFNγ expression when NK cells were isolated from within the tumor compared to the peritumor region." (PMID 35414042, 2022). "Thereafter, we assessed the autologous T-cell reactivity to the candidate neoantigens using a long peptide approach in a cultured interferon gamma ELISpot and tracked the neoantigen-specific T-cells in the tumor by T-cell receptor (TCR) sequencing." (PMID 35361728, 2022). "As interaction between T cell and tumor cell surface ligands and receptors triggers IFNγ secretion, we assayed 21 ligands and receptors that were expressed in A375 for modifications by B3GNT2." (PMID 35338135, 2022). "To compare the anti-tumor potency (measured as IFNγ secretion following co-incubation with CD19 expressing tumor lines) of fresh versus cryopreserved infusion products, we examined IFNγ secretion after co-culture of CAR T cells with various targets." (PMID 36276077, 2022). "PD-L1, an immune inhibitory protein, is often upregulated in tumor cells by interferon-gamma secreted from effector T cells when tumor antigens are recognized." (PMID 35186729, 2022). "In these circumstances, treating IFNγ-insensitive tumours with ICB is ineffective, thus demanding different approaches or a combination with ICB." (PMID 35982220, 2022). "Throughout our in vitro experiments, STUB1 consistently constrains the IFNγ sensing across several murine and human tumour cell lines." (PMID 35982220, 2022). "When admixed with tumor cells proficient in IFNγ signaling however, IFNγ-resistant cells can grow out32." (PMID 35395848, 2022). "This is in line with a recent report that CAR T-cells reshape the TME and recruit and activate host-immune cells to the tumor through IFNγ and IL-1230." (PMID 36075914, 2022). "One can mention, the presence of obstacles in the tumor stroma that impede T cells from reaching cancer cells and will limit the amount of IFNγ produced." (PMID 36189315, 2022). "Interferon-gamma (IFNγ) is one of the prosurvival factors in the tumor microenvironment of CLL cells, and it is of particular interest for the following reasons." (PMID 36209148, 2022). "Subsequently, B cell IFNγ was shown to play an important role in Th1 responses that promote allograft and tumor rejection, autoimmune arthritis, and antibacterial responses." (PMID 35359977, 2022). "Infiltration of CTLs and type I Th (Th1) in the tumour is associated with a “hot” TME and a favourable prognosis, as these cells secrete IFNγ and induce tumour cell lysis." (PMID 36140243, 2022). "CD8+ T cells combines with T-cell receptors and tumor cells to generate IFNg, TNF, and granzyme B and eliminate tumor cells." (PMID 36505472, 2022). "PD-L1 status was closely related to tumor-infiltrating lymphocytes, particularly IFNγ-producing T-cells, which were more abundant in SMAD4-expressing tumors." (PMID 35155243, 2022). "Apart from acting on tumor cells, IFNγ produced by antigen-stimulated CAR T cells has been shown to reprogram the tumor microenvironment leading to beneficial effects on CAR T cells." (PMID 36189315, 2022).
tumor (continued). "Driven by memory B cells and a range of cytokines (including TNF, IL-2, IL-6, and IFNγ), T cells home to the tumor bed and release perforin and granzyme or Fas/FasL pathways to destroy tumor cells." (PMID 36704336, 2022). "We then made use of the immunogenicity of this model and examined the role of tumor cell–intrinsic IFNγ signaling in the long-term therapeutic effect of KRASG12C inhibitors." (PMID 35857848, 2022). "Monocyte from PBMCs were cultured in a medium with GM-CSF and IL-4, followed by pulsing with hypochlorous acid (HOCl)-oxidized whole tumor cell lysate and maturation with LPS and IFNγ." (PMID 36011029, 2022). "Breast cancer gene 1 (BRCA1) tumor suppressor acts in concert with STAT1 to differentially activate the transcription of a subset of IFNγ target genes and mediates growth inhibition by this cytokine." (PMID 35456913, 2022). "Intriguingly, in heterogeneous tumors comprising both IFNγ-sensing and insensitive tumor cells, the latter cells can be protected through bystander PD-L1 expression." (PMID 35395848, 2022). "The antitumor activity of UCART123 on these tumor cells was assessed in vitro using the cytotoxicity, degranulation, and IFNγ release assays." (PMID 35484100, 2022). "Our data also confirmed our conjecture that the proportion of activated CD8+ T, natural killer (high expression of IFNγ or CD107a), and Th17 cells in tumor tissues and peripheral blood of CHMACS-treated mice was markedly higher." (PMID 36147322, 2022). "For example, anti-CTLA-4, anti-PD1 and other immune checkpoint inhibition therapies lead to elevated interferon-gamma (IFNγ) in the tumor microenvironment because of increased IFNγ expression in immune cells." (PMID 35205640, 2022). "PA gene set expression also correlated with IFNγ or cytotoxic T-cell single-sample gene set enrichment analysis (ssGSEA) scores across TCGA tumor types." (PMID 36052016, 2022). "In the 1990s, endogenous IFNγ was demonstrated to protect the host against transplanted, chemically induced and spontaneous tumor growth." (PMID 35251003, 2022). "In accordance with such a connection, IFNG mRNA in OC tumor tissue, intratumoral interferon regulatory factor (IRF)‐1 and genes linked to IFN signaling have been associated with a favorable clinical outcome." (PMID 35451191, 2022). "Interestingly, recent studies have shown that inhibiting EGFR signalling may reduce tumour cell-intrinsic EGFR-induced programmed death-ligand 1 (PD-L1) upregulation, as well as extrinsic IFNγ-induced signals associated with CD8+ T cell infiltration into the tumour microenvironment (TME)." (PMID 35057796, 2022). "Interferon gamma and LPS inhibited macrophage-dependent tumor cell extravasation while the Th2 cytokine interleukin-4 (IL4) enhanced this process." (PMID 36077870, 2022). "The presence of CD8+ tumor-infiltrating lymphocytes (TILs) and interferon gamma (IFNγ) response signatures have been shown to be predictive biomarkers for ipilimumab response in mCRPC." (PMID 35603186, 2022). "Among lymphocytes separated from four lymph nodes, one sample from LN#21 showed the tumor-reactivity measured by an IFNγ ELISPOT assay after the co-culture with tumor-cells." (PMID 35606862, 2022). "Immune checkpoint blockade therapy can lead to upregulation of IFNγ and ultimately eliminate tumor cells." (PMID 35069712, 2022). "We attributed these observations to the physiological role of STUB1 to downregulate the level of IFNGR1 on tumour cells’ surface, thereby reducing their ability to sense IFNγ—a key cytokine secreted by activated T cells and NK cells." (PMID 35982220, 2022).